CDH1 (cadherin 1)
Diseases named in the same sentence as CDH1 in open-access papers (continued):
Sharing a sentence is not in itself a finding about the gene and the disease.
ovarian carcinoma (continued). "A meta-analysis was conducted to evaluate the potential role of CDH1 promoter methylation in ovarian cancer." (PMID 27067410, 2016). "However, the association between CDH1 promoter methylation and ovarian cancer remains unclear." (PMID 27067410, 2016). "As expected, ovarian cancer stroma, which is more mesenchymal-like, has a significantly lower CDH1 level than its carcinoma counterpart (p = 0.004)." (PMID 26549805, 2015). "PITX2-induced TGF-β pathway regulated the expression of invasion-associated genes, SNAI1, CDH1 and MMP9 (p < 0.01) that accounted for enhanced motility/invasion of ovarian cancers." (PMID 26298390, 2015). "Neither peritoneal (p = 0.0177) nor fallopian tube carcinoma (p = 0.459) shows differential expression of CDH1 with ovarian carcinoma." (PMID 26549805, 2015). "Consistent with this notion, an N to E-cadherin switch occurs in ovarian cancer while the expression of cadherin 11 has been shown to suppress cell migration." (PMID 23359820, 2013). "Ovarian carcinoma cell line OVCAR4 was unusual in having high expression of both CDH1 and VCL (arrow)." (PMID 22570691, 2012). "Cadherins, in particular CDH1 (E-cadherin), are known to contribute to invasiveness and stem cell like properties in ovarian cancer." (PMID 23194409, 2012). "In case of the ovarian carcinoma cell lines OVCAR-5, OVCAR-4 and NCI/ADR-RES, the methylation status of CGIs associated with the genes ABCB1, BRCA1, CDH1, DNAJC15, and SULF2 was connected to the expression of the genes." (PMID 20544021, 2010). "The process of shedding of CDH1 has recently been described for ovarian cancer cells, in support of our mass spectrometry based investigations." (PMID 18560578, 2008). "Nonetheless, the majority of these genes are common to all subtypes of ovarian cancer, and several have been previously implicated in its pathogenesis, including TACSTD1 (Ep-CAM), CDH1 (E-cadherin), KLF5 (Kruppel-like factor 5) and ERB-B3." (PMID 16508639, 2006). "Significant deletions were observed in regions such as 5q11-13, frequently reported as loss of heterozygosity (LOH) in ovarian cancer, 8p23 encoding DBC1 (deleted in breast cancer 1 gene), 10p24 harboring PTEN, 16q24 encoding CDH1 (E-cadherin) and FANCA, and 19q13.3 encompassing STK11 (LKB1)." (PMID 40953111, 2025). "In addition, PF treatment exerts powerful anti-cancer effects via the upregulation of CDH2, the downregulation of CDH1, and the inhibition of the NF-kB signaling pathway in ovarian cancer cells and cisplatin-resistant ovarian cancer cells." (PMID 38140352, 2023). "In addition, the overexpression of Ralyl can inhibit the MAPK and CDH1 signaling pathways, thereby inhibiting the development of ovarian cancer." (PMID 35309141, 2022). "The most frequent tumor associated with CDH1 germline mutations was BC (33/54, 61.1%), following prostate cancer (PC) (9/54, 16.7%), CRC (7/54, 12.9%), abdominal carcinosis (Ca) (2/54, 3.7%), ovarian cancer (OC) (1/54, 1.8%), thyroid cancer (ThC) (1/54, 1.8%), and tongue cancer (ToC) (1/54, 1.8%)." (PMID 34066044, 2021). "To exemplify the power of NeDRex to extract biologically meaningful pathways from starting seeds, we used the ovarian cancer (OC) associated genes from NeDRexDB (AKT1, ALPK2, CDH1, CTNNB1, EPHB1, OPCML, PIK3CA, PRKN) and constructed disease module using the MuST algorithm." (PMID 34824199, 2021).
ovarian carcinoma (continued). "Importantly, knockdown of CDH1 overturned the prohibitive impacts of silencing miR-106a on proliferation, invasion and glycolysis, and the promotion effect on apoptosis in ovarian cancer cells." (PMID 32714095, 2020). "Considering that miR-106a can regulate the expression of CDH1 in ovarian cancer cells, we further explored whether CDH1 could in turn affect the function of miR-106a on ovarian cancer cells." (PMID 32714095, 2020). "Similarly, CDH1 knockdown recovered the inhibition effects of miR-106a inhibitor or circ-ITCH overexpression on the progression of ovarian cancer cells." (PMID 32714095, 2020). "Importantly, circ-ITCH up-regulated the protein level of CDH1 by sponging miR-106a in ovarian cancer cells." (PMID 32714095, 2020). "Moreover, our data clarified that circ-ITCH repressed proliferation, invasion, glycolysis, and promoted apoptosis of ovarian cancer cells by targeting the miR-106a/CDH1 pathway." (PMID 32714095, 2020). "Together, these data suggested that upregulation of circ-ITCH could block the growth of ovarian cancer cells by regulating the miR-106a/CDH1 axis in vivo." (PMID 32714095, 2020). "Given the targeting relationship between miR-106a and circ-ITCH or CDH1 in ovarian cancer cells, we further explored whether circ-ITCH could regulate CDH1 expression." (PMID 32714095, 2020). "Finally, we identified higher methylation in CDH1 gene in chemoresistant ovarian cancer cells compared to the chemosensitive ovarian cancer cells." (PMID 30653577, 2019). "CDH1 is upregulated in proliferating ovarian cancers, in which its suppression inhibits their proliferation and its proliferation-promoting effects in this context have been shown to occur via mitogen-activated protein kinase kinase/extracellular signal-regulated kinase pathway activation." (PMID 28750639, 2017). "Subgroup analysis based on the ethnicity suggested that the CDH1 promoter methylation status was significantly increased risks of ovarian cancer in Asian population and Caucasian population (OR = 13.20, 95 % CI = 6.12 - 28.45; OR = 3.84, 95 % CI = 1.52 - 9.74; respectively)." (PMID 27067410, 2016). "CDH1/E-cadherin, the founding member of the CDH/cadherin family, undergoes loss-of-function mutations across multiple tumor types such as breast, gastric, colorectal and ovarian cancer." (PMID 27093186, 2016). "CDH1 -160A allele carriers have a significantly elevated risk for endometrial cancer but not for cervical cancer and ovarian cancer." (PMID 27349965, 2016). "In addition, we also assess the relationship between CDH1 promoter methylation and clinicopathological features in ovarian cancer." (PMID 27067410, 2016). "Furthermore, a multivariate Cox regression analysis of CDH1 gene expression levels and known ovarian cancer prognostic factors, such as stage, grade, surgical debulking status, histology and age, is provided." (PMID 26549805, 2015). "However, whether CDH1 could be co-regulated by circRNA and miRNA to affect cell function in ovarian cancer remains further investigated." (PMID 32714095, 2020). "Moreover, the results supported that circ-ITCH could up-modulate the level of CDH1 by sponging miR-106a in ovarian cancer cells." (PMID 32714095, 2020). "Our integrated computational and clinical analyses indicate that the piR-823/PIWIL1/DNMT3B/CDH1 axis is a putative epigenetic regulator of EMT and cancer stemness in ovarian cancer." (PMID 41596471, 2026).
ovarian carcinoma (continued). "Genes that contributed to the most variation between subtypes included known biomarkers and master regulators of ovarian cancer subtypes (MUC16 and PAX8) and many keratin and cadherin genes (KRT19, KRT7, KRT8, CDH6, and CDH1)." (PMID 39131380, 2024). "The results showed that GRB7 was positively correlated with HER2 and CDH1 in CCLE proteomics data, and GRB7 was positively correlated with HER2 and HER2_pY1248 in pan-cancer and ovarian cancer." (PMID 39204147, 2024). "In the context of ovarian cancer, such tumor suppressor genes included BRCA1, RASSF1A, E-cadherin (CDH1), HIC1, APC and the HOX genes, among others." (PMID 35740550, 2022). "The lncRNA ATB binds to EZH2 and downregulates the expression of DAB2IP, CDH1, LATS2, FOXC1 and CDX1, thus facilitating the progression of ovarian cancer." (PMID 34890108, 2022). "A dataset from patients with ovarian cancer showed a strong correlation between NAE1 and CDH1 (r = 0.5, p = 1 × 10−27)." (PMID 33573293, 2021). "After siRNA-EPYC interference, the invasion and metastasis ability of ovarian cancer cells was weakened, while the expression of SNAI2 was down-regulated and the expression of CDH1 is increased." (PMID 34888227, 2021). "Taken together, circ-ITCH impeded cell proliferation, invasion and glycolysis by regulating the miR-106a/CDH1 axis, which was in agreement with previous reports that circ-ITCH retarded ovarian carcinoma progress by targeting the miR-145/RASA1 axis." (PMID 32714095, 2020). "In this report, we examined the expression of circ-ITCH in ovarian cancer tissues and cells and revealed a network of circ-ITCH/miR-106a/CDH1." (PMID 32714095, 2020). "Aim of present study is to investigate promoter methylation of CDH1 and VIM gene and etiology of epithelial ovarian cancer (EOC)." (PMID 31653136, 2019). "During this process, ovarian-cancer cells upregulate mesenchymal genes such as TWIST1 and ZEB1, and decrease the expression of genes such as CDH1, an epithelial gene for E-cadherin." (PMID 30200478, 2018). "HDAC3 inversely correlates with CDH1 expression in ovarian carcinoma, and HDAC3 siRNA knock down in ovarian carcinoma cells reduced cell migration and increased CDH1 expression." (PMID 26918727, 2016). "Shared targets of methylation include the promotor regions of p21, p16, MGMT, BRAC1, MLH1, HOXD11, CDH1 (E-cadherin), TGF-R, ARHI, and RASSF1A in breast and ovarian cancer." (PMID 27213343, 2016). "By using four ovarian cancer cell lines representing different EMT phenotypes, PEO1 (E), OVCA429 (IE), SKOV3 (IM), Hey (M), the induction of CDH1 expression by Mocetinostat, Entinostat and CI994 was only greatly enhanced in the mesenchymal lines SKOV3 and Hey." (PMID 27551531, 2016). "Except ovarian carcinoma-derived OVCAR cells, which expressed CDH1 and KRT8 but barely any of the analyzed mesenchymal markers, significant IGF2BP1 expression was only observed in mesenchymal-like tumor- or metastases-derived cells." (PMID 23677615, 2013). "An overlapping set of seven genes (ABCB1, APC, BRCA1, CDH1, DNAJC15, HIC1 and SULF2) displayed the same methylation changes in the examined set of ovarian carcinoma cell lines." (PMID 20544021, 2010). "Specific methylation was found in cervical cancer (including CDH1, DAPK, MGMT and MINT2), endometrial cancer (CASP8, CDH13, hMLH1 and p73), and ovarian cancer (BRCA1, p14, p15, RIZ1 and TMS1)." (PMID 16928264, 2006). "Similarly, we observed that silencing TGFBI in SKOV-3 and Caov-3 cells resulted in increased expression of CDH1 (E-cadherin) and decreased CDH2 (N-cadherin), suggesting that TGFBI affected the metastatic capabilities of ovarian cancer cells via EMT reprogram." (PMID 38395907, 2024).
ovarian carcinoma (continued). "In this study, the expression of CDH1 was significantly reduced after down-regulation of WT1, which indicates that in SKOV3 ovarian cancer cells, down-regulation of WT1 to promote its migration and invasion may be partly by inhibiting the expression of CDH1." (PMID 34692659, 2021). "Methylation of hMLH1, analyzed in 138 plasma samples predicted poor survival (hazard ratio: 1.99) while CDH1, CDH13, and APC (out of a 15 gene panel) analyzed in peritoneal fluid from 57 ovarian cancer patients could predict overall survival." (PMID 31608277, 2019). "E2 promotes migration and invasion in several ovarian cancer cell lines and can also induce epithelial-to-mesenchymal transition (EMT), as shown by changes in morphology, SNAI1 induction, and decreased CDH1 (E-cadherin)." (PMID 29973689, 2018). "In this study, the expression of VIMENTIN, a marker for mesenchymal cells, was opposite to the CDH1 expression, thus may support the EMT/MET dynamic interconversion during ovarian cancer progression." (PMID 27601996, 2016). "Among these, CTNNB1, CDH1, XRCC5 are important ovarian cancer genes." (PMID 25803614, 2015). "Importantly, microarray and quantitative RT-PCR analysis revealed that G9a regulates a cohort of tumor suppressor genes including CDH1, DUSP5, SPRY4, and PPP1R15A in ovarian cancer." (PMID 25115793, 2014). "We compared hypermethylation of MGMT, CDH1, RAR-β and SYK promoters in ovarian carcinoma (OC)." (PMID 14970867, 2004). "Four ovarian cancer cell lines (PEO1, OVCA429, SKOV3, and HEYA8) representing the E, Intermediate E (IE), Intermediate M (IM), and M states along the EMT spectrum were examined at the two classical E and M genes of the cadherin family – E-Cadherin (CDH1) and N-Cadherin (CDH2)." (PMID 35637517, 2022). "In addition, the expression of ZIP13 in the ovarian cancer samples was positively correlated with those pro-metastasis genes, such as Snail, Slug, FN1, and was negatively correlated with that tumor suppressor CDH1 (E-cad) gene." (PMID 34154618, 2021). "Chao and his colleagues reported that LMX1A could inhibit the EMT pathway by upregulating the epithelial marker CDH1 and downregulating the mesenchymal markers CDH2 and FN1 by repressing the EMT-related transcription factors SNAIL, SLUG, and SIP1 in ovarian cancer." (PMID 32751497, 2020). "Furthermore, recent study of various ovarian cancer types showed that expression of membrane CDH1 was almost not detected in normal ovarian epithelium, but was higher in benign tumors, and progressively decreased in borderline or malignant tumors and in metastatic lesions." (PMID 27601996, 2016). "TGFβ stimulation in ovarian cancer cells treated with non-specific DNMT inhibitor SGI-110 or guadecitabine led to increased activity and nuclear localization of particularly DNMT1 and prevention of CDH1 silencing, which suggests a TGFβ-DNMT1-CDH1 pathway." (PMID 37566041, 2023).
prostate carcinoma (486 papers, 1999 to 2026). A carcinoma that arises from epithelial cells of the prostate gland. "Most notable of these was CDH1, a classic prostate cancer driver gene that its loss has been previously associated with radioresistance." (PMID 39166898, 2024). "Apart from that, the metastatic progression of prostate cancer is also closely associated with two genes, namely E-cadherin (CDH1) and KAI1 genes." (PMID 36826044, 2023). "Since we have previously shown that SAG knockdown causes DEPTOR accumulation to block mTORC signaling in prostate cancer cells, we focused our study on CDH1." (PMID 36548081, 2023). "CDH1 deletion in prostate cancer is strongly associated with early recurrence of prostate cancer, a high Gleason score, and advanced tumor stage." (PMID 37190171, 2023). "A C/A polymorphism (SNP rs16260) at position –160 from the transcriptional start site decreases the activity of the CDH1 promoter by about 70% and is linked to increased risk for prostate cancer." (PMID 36243981, 2022). "Loss of heterozygosity toward the homozygous mutation of CDH1, the gene that encodes E-cadherin, is involved in cancer metastasis, particularly for breast, liver, and prostate cancers." (PMID 34502188, 2021). "The loss of CDH1 (E-cadherin) expression is associated with metastatic progression of prostate cancer." (PMID 31060254, 2019). "Decreased CDH1 expression has been associated with more extensive metastases and poor overall survival in prostate cancer patients." (PMID 22191037, 2011). "A racial difference in the methylation status of the GSTP1, CD44, ESR, and CDH1 genes is associated with prostate cancer." (PMID 20671914, 2010). "Within this non-coding RNA, an A/C SNP at position −160 from the CDH1 transcription start site is associated with significantly increased prostate cancer risk as a result of increased recruitment of epigenetic enzymes and reduced activity of the CDH1 promoter in the presence of the A allele." (PMID 36243981, 2022). "In addition, in hereditary diffuse gastric cancer (HDGC), the hub gene CDH1 mutations are connected with an increased incidence of lobular carcinoma of the breast, and possibly, prostate cancer and colorectal carcinoma." (PMID 32093341, 2020). "CDH1 and proliferative markers also correlated in a study of endometrial cancer and have been associated with malignant and metastatic potential in bladder and prostate cancer cell lines." (PMID 28750639, 2017). "In addition, the remaining altered genes that are not depicted in the KEGG Pathway schematic, including ESR2 (−5.26, p = 0.013) and CDH1 (−2.08, p = 0.019), are implicated in prostate cancer progression." (PMID 25799167, 2015). "The results showed that the expression levels of CDH2, SNAI1, ZEB1, and ZEB2 were significantly downregulated in prostate cancer compared to controls, while the expression of CDH1 was significantly upregulated." (PMID 40693059, 2025). "Previous studies have revealed that prostate cancer tissue samples have substantially lower expression of CDH1 than benign prostatic hyperplasia (BPH) patient tissue samples." (PMID 40693059, 2025). "While our multi-database integration (GEPIA, ENCORI, DIANA tools) strengthens the validity of miR-34a-5p’s role in EMT regulation, we acknowledge contradictory reports on CDH1’s function in prostate cancer." (PMID 40693059, 2025). "Contradictory results were observed for GEPIA, which revealed that in prostate cancer, CDH1 was considerably increased in comparison to the control group." (PMID 40693059, 2025). "A study reported that miR-N5 targets the 3’-UTR of CREBBP to suppress its expression, which in turn mediates H3K56 acetylation in the promoter regions of EGFR, β-catenin, and CDH1 in prostate cancer." (PMID 38493218, 2024). "NFkB activation has been linked to the inhibition of CDH1 expression, thus promoting EMT of prostate cancer cells." (PMID 38675711, 2024).